TPO (thyroid peroxidase)
Diseases named in the same sentence as TPO in open-access papers (continued):
Sharing a sentence is not in itself a finding about the gene and the disease.
autoimmune thyroid disease (continued). "Among the offspring of mothers with elevated levels of autoantibodies involved in autoimmune thyroiditis (e.g., Thyroid Peroxidase Antibody—TPO-Ab) during pregnancy, the odds of autism increased by 80% (OR = 1.78)." (PMID 40869088, 2025). "In patients (mainly women) with autoimmune thyroiditis, metformin was found to decrease thyroid peroxidase and thyroglobulin antibodies." (PMID 40284437, 2025). "Autoimmune thyroiditis, most commonly marked by elevated anti-thyroid peroxidase (Anti-TPO) antibodies, is one of the most prevalent autoimmune conditions among women of reproductive age." (PMID 41303060, 2025). "Thyroid autoimmunity, characterized by the presence of thyroid peroxidase antibodies (TPO-Ab) and thyroglobulin antibodies (TgAb), is a common phenomenon among women of reproductive age." (PMID 41503315, 2025). "Other regions of the TPO gene have also been analyzed, further supporting the gene’s role in thyroid autoimmunity." (PMID 40650076, 2025). "Anti-TPO antibodies can be detected in almost all mothers with autoimmune thyroiditis (AT), and are considered to reflect the severity of lymphocyte infiltration in the thyroid gland." (PMID 40128881, 2025). "For example, a meta-analysis of randomized controlled trials revealed that vitamin D supplementation led to a significant decrease in TPO antibody titers, suggesting a direct impact on thyroid autoimmunity." (PMID 40822954, 2025). "The presence of antithyroid antibodies (anti-TPO and anti-TG) and autoimmune thyroid disease indicates shared immunological mechanisms in the pathogenesis of both conditions." (PMID 40075855, 2025). "Autoantibodies to thyroid peroxidase (TPOAb) and thyroglobulin (TgAb) define preclinical autoimmune thyroid disease (AITD), a common endocrine disease characterized by T- and B-lymphocyte infiltration of the thyroid gland." (PMID 38996042, 2025). "Both thyroglobulin (Tg) and thyroid peroxidase (TPO) are major autoantigens in autoimmune thyroid diseases." (PMID 40650076, 2025). "Thyroid autoimmunity primarily refers to the presence of thyroid autoantibodies, such as anti‐thyroid peroxidase and anti‐thyroglobulin antibodies, commonly observed in thyroid disorders like Hashimoto's thyroiditis." (PMID 40325291, 2025). "Standard biomarkers include total IgE, anti-TPO, and anti-TG antibodies, as well as thyroid function tests, which are particularly important due to the well-known association of CSU with autoimmune thyroid diseases, such as autoimmune thyroid disease." (PMID 40075855, 2025). "This is the reason why the most recent task force recommendations for the diagnosis and management of thyroid disease during pregnancy and postpartum, suggest to assess only anti-TPO antibodies when testing for thyroid autoimmunity." (PMID 40128881, 2025). "Of those examined, 37.9% tested positive for anti-TPO antibodies, indicating the presence of concurrent thyroid autoimmunity." (PMID 40650029, 2025). "The role of thyroid autoimmunity in HE pathogenesis is further complicated by the fact that elevated serum anti-TPO antibody levels are present in approximately 10% of healthy adults and that this prevalence increases with age." (PMID 40149702, 2025). "Emerging evidence suggests a role for autoimmune and inflammatory processes, with anti-thyroid peroxidase antibodies (anti-TPO) and high-sensitivity C-reactive protein (hsCRP) as potential markers of thyroid autoimmunity and systemic inflammation." (PMID 39902025, 2025). "In patients with HT, low levels of vitamin D have been correlated with increased levels of thyroid peroxidase antibodies (anti-TPO), which are indicative of thyroid autoimmunity." (PMID 40822954, 2025). "Our study observed a low prevalence of thyroid autoimmunity markers, such as anti-thyroid peroxidase (TPO) antibodies, among the participants, which contrasts with the findings in other studies." (PMID 40863211, 2025).
autoimmune thyroid disease (continued). "FT4: ▴ SFTSH: ▾ SF* In mothers with ID, TSH was ↑, FT4 was ↓, and TPO-Ab was ↔.* In mothers with ID, subclinical hypothyroidism and thyroid autoimmunity (TPO-Ab > 60 kIU/L) were ↑." (PMID 39944206, 2025). "Thyroid autoimmunity has been referred to as the presence of antibodies to thyroid peroxidase, TSH receptor, and thyroglobulin." (PMID 39607709, 2025). "Autoimmune thyroid diseases (AITDs) are a group of diseases characterized by the breakdown of tolerance to thyroid autoantigens [primarily thyroid peroxidase (TPO), thyroglobulin (Tg), and the thyrotropin receptor (TR)]." (PMID 40558577, 2025). "Autoimmune thyroid diseases are the most prevalent organ-specific state, affecting 2% to 5% of the TS population, and the occurrence of thyroid peroxidase antibodies (anti-TPO) indicates the presence of autoimmune thyroid disease." (PMID 37758506, 2024). "Two patients (18.18%) had a clinical history of autoimmune thyroiditis, while another two patients (18.18%) had antithyroid antibodies (anti-thyroglobulin and anti-thyroid peroxidase)." (PMID 38541203, 2024). "It has been found that the cag-A positive Hp strains show a nucleotide sequence similar to the thyroid peroxidase (TPO) sequence, illustrating that serum CagA positive increases the risk of autoimmune thyroid disease." (PMID 38386169, 2024). "The same trend was observed in male patients, where anti-TPO antibody levels, the percentage of patients presenting with anti-TPO antibodies, and thyroid autoimmunity were significantly higher in male SSc patients than in male controls." (PMID 38256549, 2024). "In cases of polycystic ovary syndrome (PCOS), where hormonal imbalances are common, women with higher estradiol levels are more likely to exhibit positive anti-TPO antibodies, indicating a potential link between estrogen and autoimmune thyroid disease." (PMID 39513876, 2024). "Proteins identified in the SARS-CoV-2 proteome, such as the spike protein, membrane protein, and nucleoprotein, share similar peptide sequences with TPO, leading to this cross-reactions and, subsequently, thyroid autoimmunity." (PMID 39967901, 2024). "In a separate study, it was found that out of 491 patients diagnosed with T1D, 122 tested positive for the TPO antibody, including 15 with autoimmune thyroid disease." (PMID 39568808, 2024). "The same trend was observed in male patients, where anti-TPO antibody levels and the percentage of patients presenting with anti-TPO antibodies and thyroid autoimmunity are significantly higher in male SSc patients compared to male controls." (PMID 38256549, 2024). "The predominant antigens involved in thyroid autoimmunity are thyroid peroxidase (TPO), thyroglobulin (Tg) and the TSH receptor (TSHR)." (PMID 39770919, 2024). "Hashimoto’s thyroiditisin our study was considered based on clinical criteria: increased TSH, low free T4, positive anti-TPO, and measurement of TPO antibody used in our study as a strong parameter in the screening for thyroid autoimmunity." (PMID 39807417, 2024). "Anti‐TPO is a good indicator of thyroid autoimmunity and thyroid gland damage increases as anti‐TPO level increases." (PMID 38370054, 2024). "Considering thyroid autoimmunity, preeclampsia was diagnosed in 2.2% of women positive for TPO-Ab (> 60 U/mL) or Tg-Ab (> 33 U/mL) in early pregnancy (aOR 0.86 (95% CI: 0.6–1.2))." (PMID 39090762, 2024). "Half of the patients had elevated TPO-Ab, and a significant proportion had elevated anti-Tg, which are both markers of autoimmune thyroid disease." (PMID 37374063, 2023). "Our results are in line with these studies, as we defined a reliable correlation between blood serum and follicular fluid levels of anti-thyroid peroxidase autoantibodies (Rs = 0.992, p = 0.00001) in infertile women affected by autoimmune thyroiditis." (PMID 36902134, 2023). "Thyroglobulin autoantibodies (A-TG) and thyroid peroxidase autoantibodies (A-TPO) are markers of thyroid autoimmunity." (PMID 37706034, 2023).
autoimmune thyroid disease (continued). "Total IgE levels and thyroid autoimmunity (levels of anti-thyroid peroxidase [TPO] IgG) were measured before omalizumab treatment." (PMID 37108654, 2023). "Serum thyroid peroxidase antibody and thyroglobulin antibody are detected in association with the activation of NLRP3 in autoimmune thyroiditis patients." (PMID 36673016, 2023). "The observed frequency of CKD patients with concurrent autoimmune thyroid disease in this study 14/184 (7.6%) for Tg-Abs and 29/184 (15.8%) for TPO-Abs are partially close to 82/1032 (7.9%) for Tg-Abs and TPO-Abs reported in a retrospective study in China." (PMID 37623811, 2023). "Biochemical markers of thyroid autoimmunity, i.e., anti-TG or anti-TPO Ab positivity or thyroiditis diagnosed by ultrasonography, were significantly higher and more frequent in patients with psoriatic arthropathy." (PMID 38192953, 2023). "The study found that the rs2048722 CT + TT genotype of thyroid peroxidase (TPO) in the Japanese population had markedly higher serum anti-thyroid peroxidase antibody (TPOAb) levels compared with CC genotype autoimmune thyroid disease patients." (PMID 36737753, 2023). "Autoimmune thyroid disease demonstrated by positive Tg-Abs and TPO-Abs were observed among approximately 7.9% of CKD patients." (PMID 37623811, 2023). "After exposure to an iodine-rich diet, the extent of the autoimmune thyroiditis and the levels of thyroglobulin and TPO autoantibodies were higher in the NOD.H2h4 mice than in the NOD.H2k mice, in which TPO antibodies were essentially absent." (PMID 35572553, 2022). "CD: celiac disease, AITD: autoimmune thyroid disease, HT: Hashimoto’s thyroiditis, GD: Grave’s disease, anti-TPO: anti-thyroid peroxidase." (PMID 35911325, 2022). "The role of anti-thyroid peroxidase (anti-TPO) antibodies in the pathogenesis of autoimmune thyroid disease (AITD) is negligible." (PMID 33650064, 2022). "One experimental study found that Tg-Ab and Tg were deposited in the thyroid gland of obese strain chickens, and Tg-Ab was generated more rapidly in an autoimmune thyroiditis rat model than TPO-Ab." (PMID 35395842, 2022). "Se supplementation is expected to improve inflammatory status in patients with autoimmune thyroiditis, especially in those with high activity, and has been demonstrated as effective in reducing the thyroid peroxidase antibodies titer." (PMID 35684035, 2022). "The study is, however, limited by our inability to measure markers of thyroid autoimmune status such as Thyroid peroxidase antibody, and serum selenium levels, another micronutrient whose deficiency is associated with thyroid dysfunction." (PMID 35120491, 2022). "Among thyroid antibodies, anti-thyroid peroxidase (anti-TPO) antibodies are the most frequent autoantibodies in patients with autoimmune thyroid disease (AITD), present in approximately 90% of the patients with Hashimoto’s thyroiditis." (PMID 35415048, 2022). "Autoantibodies for each substance—called anti-Tg-antibody (TgAb) and anti-TPO-antibody (TPOAb)—tend to be elevated in autoimmune thyroid disease, and are used in diagnostics." (PMID 35741278, 2022). "LADA is most often associated with thyroid antibody TPO-Ab and autoimmune thyroid disease; nearly 20% of LADA patients with high titers of GADA have autoimmune thyroid disease, and subclinical thyroid dysfunction is the most common thyroid problem." (PMID 36090989, 2022). "Thyroid peroxidase (TPO), thyroglobulin antibodies (TGA), and TPO antibodies are commonly seen in women with autoimmune thyroid disease (AITD)." (PMID 35686265, 2022). "Although there was a tendency of better results in patients with positive ASST and increased anti-TPO antibodies, more studies are needed to evaluate the effect of plasmapheresis for patients with autoimmune thyroid disease and autoreactive urticaria." (PMID 35071772, 2022).
autoimmune thyroid disease (continued). "The diagnosis of autoimmune thyroiditis relies on the demonstration of circulating antibodies to thyroid antigens (mainly TPO and Tg) that are characterized by epitope-specific cellular immunity of CD8+ lymphocytes." (PMID 36077831, 2022). "Autoimmune thyroid disease is characterised by the generation of autoantibodies against self-antigens such as thyroid peroxidase, thyroglobulin, and thyroid-stimulating hormone receptor." (PMID 36705201, 2022). "In our study sample, we evaluated the possible influence of thyroid autoimmunity related to elevated TPO-Ab and Tg-Ab on functional outcome in euthyroidism with AIS in China." (PMID 35256895, 2022). "Both thyroglobulin (TG) and thyroperoxidase (TPO) had been found in the subepithelial immune deposits, as the main characteristic of membranous nephropathy, which may be the reason of the higher prevalence of membranous nephropathy associated with autoimmune thyroid disease." (PMID 36496400, 2022). "This should be helpful in improving our understanding of thyroid autoimmunity and developing effective inhibitors of TPO enzyme activity." (PMID 35869534, 2022). "In this setting, in other studies including patients with SA and autoimmune thyroiditis, a remarkably high incidence of positive autoantibodies against thyroid peroxidase and thyroglobulin were found." (PMID 33550991, 2021). "The majority of HE/SREAT cases are euthyroid or sub-clinically hypothyroid at presentation, but also have serological evidence to support the diagnosis of an autoimmune thyroid pre-disposition [thyroid peroxidase (TPO) and thyroglobulin antibodies]." (PMID 34061124, 2021). "Previous studies showed that 5–20% of women of childbearing age are affected by Thyroid Autoimmunity (TAI) which is characterized by the presence of anti-thyroid peroxidase (anti-TPO) and/or anti-thyroglobulin (anti-TG) antibodies." (PMID 34178319, 2021). "Thyroid autoimmunity is characterized by easily detectable production of thyroid autoantibodies, to thyroglobulin (TG) and thyroid peroxidase (TPO)." (PMID 34804698, 2021). "The combination of the decrease in anti-TPO concentrations and the observed clinical improvement suggests that thyroid autoimmunity plays a role in persisting symptoms in euthyroid HD patients." (PMID 34027377, 2021). "Additional autoAbs have also been suggested to mediate the disease heterogeneity, such as anti-thyroid peroxidase (anti-TPO) and antithyroglobulin (anti-Tg) antibodies, the essential culprits of the immune system in autoimmune thyroid diseases." (PMID 33796116, 2021). "The presence of these antibodies has been associated with a diagnosis of autoimmune disease of the thyroid, although anti-TPO is a more specific marker for autoimmune thyroiditis than TgAb." (PMID 31979063, 2020). "Among the autoimmune thyroiditis group, we found the levels of anti-TPO and anti-TG were significantly higher in patients treated by interferon beta-1b compared to patients treated by fingolimod (respectively)." (PMID 33132691, 2020). "Thyroid autoimmunity (TAI) – the presence of anti-thyroid peroxidase and/or anti-thyroglobulin antibodies – affects 8–14% of reproductively-aged women." (PMID 33239046, 2020). "The general belief is that TPO-Ab should be measured to identify autoimmune thyroiditis diseases in a manner similar to HT." (PMID 33013669, 2020). "Two thyroid antibodies that are considered indicators of autoimmune thyroiditis are anti-TPO and anti-TG." (PMID 33272321, 2020). "In one of the study among Nepalese pregnant women, thyroid autoimmunity as estimated using anti-TPO antibodies was seen in 3.3% of the women." (PMID 31320934, 2019). "Here we used anti-Tg antibodies to define thyroid autoimmunity instead of anti-TPO antibodies, which is one of the limitations of this study." (PMID 31320934, 2019). "We sought to assess the early appearance of anti-TPO and anti-Tg markers in subjects with autoimmune thyroid disease." (PMID 31467701, 2019).
autoimmune thyroid disease (continued). "Most previous studies identified smokers using questionnaires, and the presence of thyroid autoimmunity was defined with various cut-off values of TPO Ab." (PMID 30862792, 2019). "The familial clustering of autoimmune thyroid disease and the presence of anti-TPO-Ab in 16.7% to 60% of first-degree relatives of patients has been reported by several studies." (PMID 31428301, 2019). "Like PTC, FTC retains many characteristics of thyroid follicular cells, including the expression of thyroid-specific proteins such as TSH receptor, thyroid peroxidase (TPO), and thyroglobulin (Tg) that serve as targets for thyroid autoimmunity." (PMID 31791180, 2019). "We targeted to commentate anti-thyroid peroxidase (anti-TPO), anti-thyroglobulin (anti-TG) antibody levels and thyroid autoimmunity in PCOS." (PMID 29699958, 2018). "In this study, again, a majority of patients had evidence of pre-existing thyroid autoimmunity, such as a diffuse hypoechoic pattern on thyroid ultrasound, positive anti-TPO autoantibodies, and borderline TRAb titers." (PMID 29069397, 2018). "A high prevalence of anti-ENA and ANA was found to be coexisting with autoimmune thyroid disease subjects, with anti-TPO occurring prior to the onset of ANA and anti-ENA." (PMID 30911555, 2018). "Anti-thyroid peroxidase antibodies (anti-TPO Ab) and anti-thyroglobulin antibodies (anti-TG Ab) are fundamental markers of thyroid autoimmunity." (PMID 29699958, 2018). "In a previous study, high anti-TPO titer was highly indicative of the degree of hypoechoic pattern in autoimmune thyroiditis." (PMID 30349584, 2018). "Thyroid autoimmunity, presenting with increased thyroid autoantibody levels, anti-thyroid peroxidase (anti-TPO) anti-thyroglobulin (anti-TG) antibodies, is associated with vitamin D deficiency [serum 25(OH)D <50 nmol/L]." (PMID 29067607, 2017). "Thyroid autoimmunity involves a breakdown in self-tolerance to three thyroid proteins: thyroglobulin, thyroid peroxidase (TPO), and the thyroid-stimulating hormone receptor (TSHR)." (PMID 28620373, 2017). "Evidence for original antigenic sin in spontaneous thyroid autoimmunity is revealed by autoantibody interactions with immunodominant regions on thyroid autoantigens, thyroglobulin (Tg), thyroid peroxidase (TPO), and the thyrotropin receptor (TSHR) A-subunit." (PMID 29326719, 2017). "Autoimmune thyroid diseases are usually accompanied by the presence of anti-thyroid peroxidase (TPO), anti-thyroglobulin (Tg), and anti-thyroid-stimulating hormone receptor (TSHR) antibodies." (PMID 28536577, 2017). "Thyroid autoimmunity was defined by presence of anti-thyroid peroxidase, −thyroglobulin and/or -thyroid receptor antibodies." (PMID 27165095, 2016). "Autoimmune thyroid disease can also be mediated by direct binding of complement C4 to thyroid peroxidase." (PMID 27064909, 2016). "In women with low-normal TSH levels, female age (P = 0.012), oocyte numbers (P = 0.034), thyroid autoimmunity (P = 0.030) and TPO antibodies (P = 0.021) significantly affected embryo quality in univariate regression analysis." (PMID 25975563, 2015). "Thyroid autoimmunity and TPO positive antibody status occurred more often in women with high normal TSH levels (P = 0.015 and P = 0.003, respectively)." (PMID 25975563, 2015). "It has been reported in autoimmune thyroiditis that autoantibodies against thyroid peroxidase (TPO) modulate the T cell epitope repertoire." (PMID 25874890, 2015). "Women with TSH > 2.5 μIU/mL levels were more likely to demonstrate thyroid autoimmunity (P = 0.015) and TPO antibodies (P = 0.003) than women in the lower TSH group." (PMID 25975563, 2015). "Anti-TPO antibody estimation helps in establishing the etiological diagnosis of autoimmune thyroid diseases." (PMID 26435714, 2015). "One overriding limitation of this study is the use of a sole marker (anti-TPO Ab) for identifying thyroid autoimmunity in the participants." (PMID 25653881, 2015).